INSR (insulin receptor)
Diseases named in the same sentence as INSR in open-access papers (continued):
Sharing a sentence is not in itself a finding about the gene and the disease.
Stroke (2 papers, 2020 to 2025). Sudden impairment of blood flow to a part of the brain due to occlusion or rupture of an artery to the brain. "Additionally, the upregulation of insulin receptor (INSR) expression in the tibial artery was associated with a reduction in stroke incidence in patients with large-artery atherosclerotic stroke (LAS) (OR = 0.66, 95% CI = 0.46–0.95; p = 0.026)." (PMID 41209129, 2025). "Conversely, five genes (CLCN6, OGDHL, COL6A3 [MIM: 120250], INSR [MIM: 147670], and NOS3 [MIM: 163729]) were found in the “long survivor” group but not in the “stroke” group." (PMID 32898326, 2020).
tongue squamous cell carcinoma (2 papers, 2022 to 2023). A squamous cell carcinoma that arises from the tongue. "Upregulation of INSR promoted tumorigenesis and metastasis in tongue squamous cell carcinoma." (PMID 36147494, 2022).
3-M syndrome (1 paper, 2014). 3M syndrome is a primordial growth disorder characterized by low birth weight, reduced birth length, severe postnatal growth restriction, a spectrum of minor anomalies (including facial dysmorphism) and normal intelligence. "The net result is a reduction in the expression of the mitogenic INSR isoform in 3-M syndrome." (PMID 24711643, 2014).
abnormal glucose tolerance (1 paper, 2022). "The level of TNF-α in patients with abnormal glucose tolerance increases significantly; IL-6 can control the signal transduction of insulin receptor and reduce insulin sensitivity." (PMID 35399678, 2022).
adrenocortical carcinomas (1 paper, 2025). "The insulin-like growth factor 2 (IGF2) is overexpressed in 90% of adrenocortical carcinomas (ACC) and promotes cell proliferation via IGF1R and isoform A of insulin receptor (IRA)." (PMID 40038716, 2025).
anaplastic thyroid cancer (1 paper, 2021). "The ability of SOD3 to stimulate the insulin receptor activation is in line with the Gorilla analysis demonstrating a marked enrichment of metabolism-related genes in anaplastic thyroid cancer cells." (PMID 33919252, 2021).
anencephaly (1 paper, 2020). A rare neural tube defect during pregnancy, resulting in the absence of a large portion of the brain and skull in the fetus.
aortic stenosis (1 paper, 2023). Aortic valve stenosis is a aortic valve disease caused by the incomplete opening of the aortic valve. "Therefore, we speculated that when the body has IR, the insulin-receptor signaling pathway is damaged, and the proliferation and survival of osteoblasts are inhibited, thus affecting the occurrence and development of calcifying aortic stenosis." (PMID 37697065, 2023).
atopic dermatitis (1 paper, 2023). "These experimental approaches in mice included a ketogenic diet (5.7%), hypoxia-inducible factor knock-out (6.1%), insulin receptor knock-out (9.1%), dry skin (85.2%), and atopic dermatitis (129.8%)." (PMID 37153658, 2023).
atrial fibrillation (1 paper, 2021). A disorder characterized by an electrocardiographic finding of a supraventricular arrhythmia characterized by the replacement of consistent P waves by rapid oscillations or fibrillatory waves that vary in size, shape and timing and are accompanied by an irregular ventricular response. "Pharmacogenetics interaction between exposure to L-thyroxine and INSR-rs4804416 on developing atrial fibrillation by follow-up time (n = 6,802)." (PMID 34249083, 2021).
autism spectrum disorder (1 paper, 2025). A spectrum of developmental disorders that includes autism, and Asperger syndrome. "Sixteen variants in INSR have been reported to be associated with autism spectrum disorder (HGMD, accessed on 1 April 2025)." (PMID 40430072, 2025).
Bardet-Biedl syndrome (1 paper, 2024). A ciliopathy with multisystem involvement. "Similarly, in Bardet-Biedl syndrome, defects in the BBSome complex could lead to abnormal cellular localization of insulin receptor, as well as proteins involved in satiety regulation." (PMID 39017987, 2024).
behavioral disorders (1 paper, 2017). "Moreover, it was demonstrated, in a brain-specific knock out of the insulin receptor mice model, that IR in the brain altered dopamine turnover and resulted in behavioral disorders." (PMID 29084550, 2017).
celiac disease (1 paper, 2015). An autoimmune genetic disorder with an unknown pattern of inheritance that primarily affects the digestive tract. "In biopsies from celiac disease patients, minor allele carriers of the INSR rs7254060 SNP showed decreased INSR gene expression levels (INSR rs7254060; p = 0.003) and minor GLS rs6741418 carriers showed decreased GLS gene expression levels (GLS rs6741418; p = 0.009)." (PMID 26123480, 2015). "The differential expression of NTS and PPP1R12B indicate a potential role for smooth muscle contractility and cell proliferation, whereas other genes like GLS, NCALD and INSR suggests involvement of nutrient signaling and energy homeostasis in celiac disease pathogenesis." (PMID 26123480, 2015). "The differential expression of NTS and PPP1R12B indicate a potential role for smooth muscle contractility and cell proliferation in celiac disease, whereas other genes like GLS, NCALD and INSR suggests involvement of nutrient signaling and energy homeostasis in celiac disease pathogenesis." (PMID 26123480, 2015). "Seven genes were down-regulated in the biopsies of celiac disease patients, among them NTS down-regulated 3.6 fold and the INSR, APPL2, ADCY9, GLS, HSPB1 and KIF13A 1.5-2.2 fold in the patient group (p < 0.001)." (PMID 26123480, 2015).
Cerebral ischemia (1 paper, 2015). Restriction of arterial blood supply to the brain associated with insufficient oxygenation to support the metabolic requirements of the tissue. "In conclusion, ALA attenuates cerebral ischemia and reperfusion injury via insulin receptor and PI3K/Akt-dependent inhibition of NADPH oxidase." (PMID 26294909, 2015).
cerebrovascular disease (1 paper, 2024). "This hypothesis is significantly bolstered by research linking brain insulin resistance in humans to reduced arterial blood flow and cerebral perfusion, increased risk of cerebrovascular disease, and decreased vascular insulin receptor concentrations observed in the parietal cortex of AD patients." (PMID 39656485, 2024).
Chronic colitis (1 paper, 2024). A chronic inflammatory disease of the large intestine (colon, cecum and rectum). "In agreement with the qPCR results, INSR expression was found to be down-regulated in both IELs and LPLs in chronic colitis." (PMID 38243324, 2024). "The expression of INSR was found to be down-regulated in both IELs and LPLs in DSS-induced chronic colitis." (PMID 38243324, 2024). "In conclusion, INSR was specifically down-regulated in lymphocytes in chronic colitis, whereas other colonic cells showed no significant change." (PMID 38243324, 2024).
chronic hepatitis C (1 paper, 2012). "TNF-α is upregulated in patients with chronic hepatitis C (CHC) and this cytokine has been shown to interrupt insulin signaling via reduced-tyrosine phosphorylation of IRS-1 and decreased ability of IRS-1 to associate with the insulin receptor." (PMID 23049551, 2012).
colitis (1 paper, 2024). Inflammation of the colon. "Exacerbation of colitis by INSR appears to contradict with the downregulation of INSR in mucosal T-cells." (PMID 38243324, 2024). "We expected to use INSR-specific inhibitors and further investigate their effects on colitis." (PMID 38243324, 2024). "Since insulin receptor (INSR) expression was significantly reduced in IELs in DSS-induced colitis, INSR expression was analyzed in 6 human sequencing data of UC mucosa from the GEO database to verify whether this trend is equally present in human." (PMID 38243324, 2024). "We believe that the downregulation of INSR in mucosal T cells may act as a protective mechanism in colitis." (PMID 38243324, 2024). "Among the pairs screened by DEmRNA and DElncRNA joint analysis, both INSR and the INSR-regulating lncRNA, MSTRG.175050.1, showed highly significant down-regulated fold changes in colitis (INSR top10, MSTRG.175050.1 top30)." (PMID 38243324, 2024). "Insulin receptor inhibitors rather than insulin should be applied during colitis-active phase." (PMID 38243324, 2024).
Down syndrome (1 paper, 2024). "INSR and IRS1 levels positively correlated with the synapse markers, syntaxin, and PSD95, and this impairment in INSR signaling occurred early in Down syndrome before the development of AD pathology." (PMID 37611907, 2024).
endometrial tumors (1 paper, 2022). "Given the important role of insulin and INSR in cancer biology, mainly breast and endometrial tumors, it is expected that future efforts will embrace also the development of INSR-directed molecules." (PMID 36479090, 2022).
Erythema (1 paper, 2023). Redness of the skin, caused by hyperemia of the capillaries in the lower layers of the skin. "Various skin abnormalities, such as hyperkeratosis, abnormality of the plantar skin of the foot, palmoplantar keratoderma, subcutaneous nodules and erythema, were associated with GJA1, KRT1, KRT2, PSEN1 and INSR." (PMID 37185447, 2023).
gastric adenocarcinoma (1 paper, 2022). "Amplification of insulin receptor transcripts by RT-PCR detected both isoform B and isoform A mRNAs in all gastric adenocarcinoma cell lines and metastatic cells." (PMID 34554347, 2022). "Demonstration that the insulin receptor transmits a strong cell survival stimulus in gastric adenocarcinoma was unexpected." (PMID 34554347, 2022). "Objectives were to investigate if insulin promotes directly gastric adenocarcinoma cell proliferation or survival, and to explore the relative importance of the insulin receptor." (PMID 34554347, 2022). "The INSR and IGF1R genes, which encode the insulin and type I IGF receptors, were expressed in all gastric adenocarcinomas; median relative mRNA abundances were around 10 to 12 (log2)." (PMID 34554347, 2022). "Gastric adenocarcinoma cell survival depends upon insulin receptor." (PMID 34554347, 2022). "Insulin receptor knockdown reduced untreated FCS-stimulated growth of gastric adenocarcinoma cells." (PMID 34554347, 2022). "Insulin receptor was detected readily in metastatic gastric adenocarcinoma cells and cell lines." (PMID 34554347, 2022). "Amplification, deletion or relative overexpression of INSR and IGF1R were detected in 3% and 8% of gastric adenocarcinomas, respectively." (PMID 34554347, 2022). "Dependence of gastric adenocarcinoma cell survival upon insulin receptor but not type I IGF receptor indicates that IGF-1 and IGF-2 promote cell survival through the insulin receptor." (PMID 34554347, 2022).
gliosarcoma (1 paper, 2020). A rare histological variant of glioblastoma (WHO grade IV) characterized by a biphasic tissue pattern with alternating areas displaying glial and mesenchymal differentiation (WHO). "However, in our gliosarcoma patient with disease progression under entrectinib, no secondary NTRK mutation was detected, but molecular profiling revealed activation of alternative oncogenic pathways, including NF2 and insulin receptor (INSR)." (PMID 33353026, 2020).
Graves disease (1 paper, 2023). Graves' disease is an autoimmune disorder that leads to overactivity of the thyroid gland (hyperthyroidism).It is caused by an abnormal immune system response that causes the thyroid gland to produce too much thyroid hormones. "Here, we investigated in an experimental murine model of Graves’ disease, whether autoimmune GD and TED associates with bone marrow activation and whether linsitinib, an oral small molecule inhibitor of the IGF-1R and insulin receptor (IR), interferes with this activation process." (PMID 37810891, 2023). "Involvement of the Insulin receptor (IR) in the disease pathogenesis of Graves’ Disease and thyroid eye disease has, to our knowledge, not been reported yet." (PMID 37810891, 2023).
head and neck squamous cell carcinoma (1 paper, 2019). A squamous cell carcinoma that arises from any of the following anatomic sites: lip and oral cavity, nasal cavity, paranasal sinuses, pharynx, larynx, and salivary glands. "The relationship between malignancy and the overexpression of INSR is best shown in a tissue section representing the rim of a tumour, e.g., of a head and neck squamous cell carcinoma and the adjacent normal tissue." (PMID 30559346, 2019).
HIV-associated neurocognitive disorder (1 paper, 2019). HIV-associated neurocognitive disorder (HAND) remains a common complication of HIV infection in the combination antiretroviral therapy (ART) era. "Previously, we found that high levels of soluble insulin receptor (sIR) in the cerebrospinal fluid (CSF) of an HIV-infected women cohort were associated with the presence and severity of HIV-associated neurocognitive disorders (HAND)." (PMID 30972014, 2019).
Hyperkalemia (1 paper, 2023). An abnormally increased potassium concentration in the blood. "Nonetheless, male but not female KO mice showed relative hyperkalemia (compared to sex-specific WTs), suggesting the males were more sensitive to the disruption of K+ homeostasis via renal InsR deletion." (PMID 37175762, 2023).
Hypoglycemic coma (1 paper, 2022). Coma induced by low blood sugar. "Thus, it is possible that hypoglycemic coma in our animals, induced by an overactivation of the insulin receptor similar to an insulin overdose, can cause unresponsiveness and inability to feed and drink, causing the death of the animals." (PMID 35406129, 2022).
hypovitaminosis D (1 paper, 2014). "In keeping with this, there are experimental data demonstrating that hypovitaminosis D causes impairment in insulin receptor expression and insulin secretion in animal models and humans, while treatment with vitamin D improves β-cell function and glucose tolerance." (PMID 24555478, 2014).
immune deficiency (1 paper, 2023). "That is, juvenile hormone (JH)-controlled egg laying, lipid droplet utilization and insulin receptor expression are specifically compromised by the immune deficiency (Imd) and the dual oxidase (Duox) signaling in the midgut epithelium." (PMID 36984780, 2023).
ischemic cardiomyopathy (1 paper, 2025). Ischemic cardiomyopathy is a cardiomyopathy in which a weakness in the muscle of the heart due to inadequate oxygen delivery to the myocardium with coronary artery disease being the most common cause. "The expression of insulin receptor (INSR) is increased in EC-arterial cells of ischemic cardiomyopathy (ICM) patients, which may affect the signal transduction of angiogenesis." (PMID 40520009, 2025).
Lipedema (1 paper, 2022). Disorder of adipose tissue characterized by symmetric and bilateral enlargement of the lower extremities due to abnormal deposition of subcutaneous fat often in obese women. "The truncating variant in INSR, c.3079C>T; p.Arg1027* (rs121913144), is a good candidate to explain the lipedema phenotype." (PMID 35207755, 2022).
lymphedema (1 paper, 2025). Excess fluid collection in tissues, causing swelling. "Further, we assessed patient samples and found that memory T cells isolated from lymphedema fluid responded to stimulation with human insulin peptides ex vivo with a pronounced increase in insulin receptor expression, whereas autologous T cells from blood did not." (PMID 40821816, 2025).
lysosomal storage disorders (1 paper, 2024). "Fusion constructs coupling a humanized anti-insulin receptor monoclonal antibody with lysosomal enzymes are currently in phase I clinical trials for lysosomal storage disorders affecting the brain (according to the NCT02262338 Health USNIO, ClinicalTrials.gov registry and results database 2016)." (PMID 39204177, 2024).
malignant glioma (1 paper, 2021). A grade III or grade IV glioma arising from the central nervous system. "The ratios of PTBP2 exon 10 skipping/inclusion, INSR exon 11 skipping/inclusion (the ratio of INSR-A/INSR-B) and ECT2 exon 4 skipping/inclusion are indeed significantly increased in malignant glioma, especially in GBM patient samples when compared to normal brain." (PMID 34548489, 2021).
mental disorder (1 paper, 2021). A disease that has its basis in the disruption of mental process. "And an array of metabolic abnormalities and mental disorders were observed when the insulin receptor (IR) in the brain was knockdown." (PMID 34149862, 2021).
metastatic tumors (1 paper, 2024). "The genes that were upregulated in the monosomy 3/metastatic tumors (PFKP, NUP88) exhibited an average fold change (FC) of 2.06 ± 0.82, whereas the downregulated genes (INSR, RBKS, and ZBTB20) differed by an average of −1.87 ± 0.44-fold." (PMID 38673877, 2024).
Miscarriage (1 paper, 2024). A pregnancy that ends at a stage in which the fetus is incapable of surviving on its own, defined as the spontaneous loss of a fetus before the 22th week of pregnancy. "The current study demonstrates the reduction in the insulin receptor gene IRS1 expression among females who experienced miscarriages." (PMID 39205919, 2024).
monoclonal gammopathy of undetermined significance (1 paper, 2026). "We observed that expression of both INSR and IFITM1 was significantly elevated in symptomatic MM patients compared with those with monoclonal gammopathy of undetermined significance (MGUS) and smouldering MM (SMM)." (PMID 42286874, 2026).
morbid obesity (1 paper, 2012). An excess of body weight, normally defined as an individual with a body mass index greater than 35 or a body weight greater than one hundred percent of ideal body weight. "Other causes include noninsulinoma pancreatogenous hypoglycaemia syndrome (NIPHS), post gastric bypass surgery for morbid obesity and mutations in insulin receptor gene, which typically present with postprandial HH." (PMID 23032149, 2012). "NIPHS has been described in patients who have undergone gastric bypass surgery for morbid obesity and in carriers of mutations in the insulin-receptor gene." (PMID 23032149, 2012).
myocardial ischemia (1 paper, 2009). A disorder of cardiac function caused by insufficient blood flow to the muscle tissue of the heart. "It has been shown that acidosis produced by myocardial ischemia provokes the inhibition of the tyrosine kinase activity of insulin receptor." (PMID 19706162, 2009).
myocarditis (1 paper, 2012). Myocarditis is a condition that is characterized by inflammation of the heart muscle (myocardium). "Given that muscle inflammation and high carbohydrate requirements are associated, it is possible that a high dose of a fusion protein that links to the insulin receptor may also be involved in the onset of myocarditis." (PMID 22745701, 2012).
Nephroblastoma (1 paper, 2014). An embryonal neoplasm characterized by the presence of epithelial, mesenchymal, and blastema components. "In contrast, levels of IL-16; IL-31; insulin receptor (IR); immunoglobulin M (IgM); Karyopherin-a2; nephroblastoma overexpressed (NovH, also known as insulin-like growth factor binding protein 9); SCF sR; TPSB2; VEGF sR2; and sL-Selectin decreased following treatment." (PMID 25100134, 2014).
neuritis (1 paper, 2013). A neuropathy arising from inflammation of one or more nerves. "More recent studies have reported that hyperinsulinaemia blunts insulin receptor signaling and insulin-induced survival and outgrowth of neuritis in sensory neurons." (PMID 24023699, 2013).